EGF (epidermal growth factor)
Diseases named in the same sentence as EGF in open-access papers (continued):
Sharing a sentence is not in itself a finding about the gene and the disease.
prostate tumors (12 papers, 2014 to 2025). "On the other hand, PTEN loss observed in >15% of prostate tumors results in significantly higher levels of pathway activation that persists even after the removal of EGF stimulation." (PMID 30813597, 2019). "On the contrary, PTEN loss (observed in >15% of prostate tumors) results in significantly higher levels of pathway activation that, surprisingly, persist even after the removal of EGF stimulation." (PMID 30813597, 2019). "Our recent study demonstrated that Klf5 loss in Pten-null prostate tumors also activates PI3K/AKT signaling by upregulating multiple extracellular growth factors (e.g. EGF), cytokines and their receptors." (PMID 25896712, 2015). "The increased activity of the EGF/EGFR complex that is associated with prostate tumour progression leads to the activation of different downstream signalling pathways including MEKK/ERK and PI3K/AKT (Phosphoinositide 3-OH Kinase)." (PMID 24796332, 2014). "We also show that NPM1 acts as a regulator of the MAPK/ERK pathway and the EGF gene expression, which would explain the change of prostate tumour cell behaviour when NPM1 expression is altered." (PMID 24796332, 2014). "However, the bead-based ELISA reports data from the entire system and accounting for the primary prostate tumor epithelial spheroids contribution, protein levels of EGF and BMPs were comparable between controls and primary prostate tumor epithelial spheroids." (PMID 40596459, 2025). "In addition, decorin is known to suppress prostate tumor growth through inhibition of epidermal growth factor and androgen receptor pathways." (PMID 32155897, 2020). "Besides strongly stimulated androgen signalling, overexpression of the EGF growth factor is also observed in prostate tumours." (PMID 24796332, 2014). "Prostate tumor cells in senescence show p38 phosphorylation activity and low ERK activity (even in the presence of an epidermal growth factor (EGF), a very well-known ERK activator), proposed as a marker of cells undergoing dormancy." (PMID 32028565, 2020). "TENB2, also known as tomoregulin or transmembrane protein with epidermal growth factor (EGF)-like and two follistatin-like domains (TMEFF), is a proteoglycan over-expressed in human prostate tumors, and has been pursued as an ADC target." (PMID 31692898, 2019).
bladder tumor (11 papers, 1987 to 2025). "It was demonstrated that EGF-dextran conjugate labeled with 99mTc selectively accumulates in human bladder tumor tissue after instillation into the bladder before tumor resection." (PMID 30510514, 2018). "The sustained induction of hEGR1 by EGF in the RT112 bladder tumour cells for 24 and 48 h, in addition to the rapid induction seen at 1 to 2 h, indicates that further investigation of the role of hEGR1 and EGFR in bladder tumours is warranted." (PMID 17311025, 2007). "The effect of epidermal growth factor (EGF) on matrix metalloproteinase-1 (MMP1) production in two human bladder tumour cell lines, RT112 and RT4, has been investigated." (PMID 9683296, 1998). "Epidermal growth factor (EGF) receptor expression in 31 primary human bladder tumours was quantitated using both structural and functional assays and the EGF receptor gene in the same tumours was analyzed by Southern blot analysis." (PMID 3426916, 1987). "In the animal experiment, MSCs could favor VX2 bladder tumor growth and up-regulate the expression of TGFβ1, EGF, FAPa, MMP9 in VX2 tumor tissue." (PMID 31528217, 2019). "Therefore, ETK may likely act as a downstream effector of EGF/EGFR to promote bladder tumor growth and metastasis." (PMID 21408190, 2011). "Egr-1 is induced by epidermal growth factor (EGF) and has been shown to correlate to EGF receptor (EGFr) levels in bladder tumors." (PMID 19878561, 2009). "The absence of hEGR1 mRNA in the bladder tumour cells without EGF stimulation also indicates that hEGR1 is not constitutively expressed." (PMID 17311025, 2007). "The effect of EGF stimulation and its inhibition with gefitinib (‘Iressa’, ZD1839), an epidermal growth factor receptor (EGFR) tyrosine kinase inhibitor, has been investigated in two EGFR-positive human bladder tumour cell lines, RT112 and RT4." (PMID 15083203, 2004).
dry eye (11 papers, 2011 to 2023). "This study aimed to systematically assess the effect of recombinant human epidermal growth factor (rhEGF) associated with conventional drugs on the score of dry eye symptoms in patients with dry eyes after cataract surgery." (PMID 36237557, 2022). "In addition, previous studies showed that tear EGF concentration was significantly decreased in dry eye syndrome, which is the one of most common causes of corneal injury." (PMID 36355484, 2022). "Xiao, in an animal model of dry eye, also noticed a positive correlation between EGF, longer TBUT, and lower ocular surface staining." (PMID 37176566, 2023). "Related to dry eye evaluation, epidermal growth factor level in tears using enzyme immunosorbent assay is decreased and inflammatory cell infiltration into lacrimal gland were evaluated by histology in this animal model." (PMID 30423813, 2018). "Concerning evaluation for dry eye, lacrimal gland histopathology, immunohistochemistory, gene expression of inflammatory marker, and EGF concentration in tears were analyzed." (PMID 30423813, 2018). "Autologous serum eye-drops are a good candidate for dry eye treatment since they contain epidermal growth factor (EGF), vitamin A, and so on, which is essential for cell differentiation and division." (PMID 30404287, 2016). "The dry eye syndrome secondary to the direct effects on the lacrimal acinar cells of prolactin, transforming growth factor beta 1 (TGF-β1), and epidermal growth factor is found at the level of the lacrimal apparatus." (PMID 34441264, 2021). "There was an increased incidence of dry eye syndrome in pregnant women, secondary to the direct effects on the lacrimal acinar cells of prolactin, TGF beta 1, and epidermal growth factor." (PMID 34441264, 2021). "There were some published EGF eyedrops in corneal injury including dry eye syndrome; however, there have been no PK studies of EGF eyedrops." (PMID 36355484, 2022). "One study revealed that recombinant human epidermal growth factor (rhEGF) can be used in penetrating keratoplasty, refractive surgery, and the treatment of diabetic keratopathy and xerophthalmia, without resulting in adverse reactions." (PMID 35130850, 2022).
metastatic colorectal cancer (11 papers, 2011 to 2024). "Certain genetic alterations and right-sided primary tumor location are associated with resistance to anti-epidermal growth factor (EGFR) treatment in metastatic colorectal cancer (mCRC)." (PMID 38347302, 2024). "Rat sarcoma viral oncogene homolog (RAS) mutation status is routinely tested in patients with metastatic colorectal cancer to predict response to anti-epidermal growth factor therapy." (PMID 35804994, 2022). "Rechallenge with epidermal growth factor (EGFR) inhibitors represents a promising therapeutic strategy in patients with refractory RAS/BRAF wild-type metastatic colorectal cancer (mCRC)." (PMID 37046778, 2023). "Patients with metastatic colorectal cancer (mCRC) frequently experience epidermal growth factor inhibitors (EGFRI)-induced skin side effects." (PMID 35712333, 2022). "Anti-EGFR and anti-VEGF antibodies are already used to a large extent to treat metastatic colorectal cancer, therefore overexpression of genes from the EGF and VEGF pathways in sporadic EOCRC could improve the response rates to these targeted therapies." (PMID 25083765, 2014).
Alzheimer disease (10 papers, 2012 to 2025). A progressive, neurodegenerative disease characterized by loss of function and death of nerve cells in several areas of the brain leading to loss of cognitive function such as memory and language. "Further, TNS3 interacts with AD-related druggable genes EGF and HGF, which in turn interact with EGFR (eFigure-11), a gene that was recently implicated in Alzheimer’s disease through GWAS15 and itself shows strong potential as a dual drug target for cancer and AD68." (PMID 41404291, 2025). "Furthermore, EGF regulates oligodendrocyte progenitor cells, relevant to the remyelination capacity degradation in Alzheimer's disease or brain aging." (PMID 38464836, 2024). "The angiogenic, Alzheimer disease-presenilin pathway, EGF/FGF/gonadotrophin signalling, inflammation mediated by chemokine and cytokine signalling with PDGF/Notch/vascular epidermal growth factor (VEGF) and Wnt signalling pathways were a few of which had the greatest number of entities related." (PMID 28705915, 2017).
autism (10 papers, 2012 to 2025). Persistent deficits in social interaction and communication and interaction as well as a markedly restricted repertoire of activity and interest as well as repetitive patterns of behavior. "While some studies have found a correlation between decreased levels of EGF and an autism diagnosis, studies in a younger cohort observed higher levels of peripheral EGF in autistic patients." (PMID 39929953, 2025). "A second report, using multiplex bead assay, found elevated serum EGF in 77 children and adolescents with autism (aged 5–15) compared to 19 healthy, slightly older, controls." (PMID 28070266, 2017). "Using enzyme-linked immunosorbent assay (ELISA), one study documented significantly elevated serum EGF in 27 Turkish children with autism aged 2–11 years relative to age-matched typical controls." (PMID 28070266, 2017). "By contrast, other researchers found that the serum EGF levels in subjects with autism were significantly higher than those of normal control subjects." (PMID 25729218, 2015). "They found that the serum EGF levels in the subjects with high-functioning autism were significantly lower compared with those of the normal control subjects." (PMID 25729218, 2015). "Researchers examined the association of EGF, TGF-β1, and HGF genes with autism in a trio association study using DNA samples from families recruited to the Autism Genetic Resource Exchange." (PMID 25729218, 2015). "In 2007, a research group measured serum levels of EGF in 17 male subjects with high-functioning autism and 18 age-matched healthy male subjects." (PMID 25729218, 2015). "An increased frequency of EGF single nucleotide polymorphisms has been reported in ASD, as well as lower plasma EGF levels in adults with autism." (PMID 22937258, 2012). "EGF and AREG have been identified as potential genetic risk factors for autism." (PMID 33445520, 2021). "Two missense changes seen in the residues of the leader sequence of a-NRXN1 and epidermal growth factor (EGF)-like domain suggests these changes in NRXN1 might be a contributing factor in developing autism." (PMID 31744938, 2019). "However, some studies have documented decreased EGF in the plasma of subjects with autism compared to controls." (PMID 28070266, 2017). "Their results revealed a significant haplotypic association between EGF and autism, but no significant SNP or haplotypic associations were observed for TGF-β1 or HGF." (PMID 25729218, 2015). "High levels of EGF in children could contribute to accelerated postnatal brain growth in autism." (PMID 40004071, 2025). "Thus, the significance of the elevated blood circulating levels of EGF and sCD40L in our participants with autism remains unknown, especially given the high degree of within-subject variability in concentration." (PMID 28070266, 2017). "Only “modulators of immune function,” Epidermal Growth Factor (EGF) and soluble CD40 ligand were increased in autism serum." (PMID 31024350, 2019). "In this study, concentrations of EGF and HGF were assessed in the plasma of 49 children with ASD aged 2–4 years old and 31 typically developing controls of a similar age as part of the Autism Phenome Project (APP)." (PMID 22937258, 2012). "The results of the current study are consistent with other comparisons of serum EGF between children with and without autism." (PMID 28070266, 2017). "Previous studies have found decreased levels of EGF in high functioning adults with autism, but no studies have looked at children with ASD who are close to the onset of the disorder." (PMID 22937258, 2012). "The group differences observed in two of the 39 analytes tested in this study, elevated circulating EGF and sCD40L, could be construed as suggesting that dysregulation of growth and modulatory pathways, rather than systemic inflammatory responses, may occur in autism." (PMID 28070266, 2017).
fibrosis (10 papers, 2018 to 2024). the formation of excess fibrous connective tissue in an organ or tissue in a reparative or reactive process. "Urinary TNFR-1, TIMP-1, and EGF are associated with renal inflammation and fibrosis." (PMID 39229378, 2024). "The expression of various cytokines was increased in EGF-stimulated LF fibroblasts, including TGF-β1, collagen I and collagen III associated with fibrosis." (PMID 36185336, 2022). "When doubling the value of EGF, the odds of a patient exhibiting F3 or F4 fibrosis stage before antiviral treatment decreased by 2.00 times (95% CI 1.43–3.14, p < 0.001)." (PMID 35893679, 2022). "Emerging candidate biomarkers for CKD progression include surrogates of tubulointersitital injury (NGAL, IL-18, KIM-1, EGF), tubulointerstitial fibrosis (MMP-9, PIIINP, TGF-β1, BMP-7), and inflammation (MCP-1, TNFR 1/2, suPAR)." (PMID 33108507, 2021). "Previous studies have identified a correlation between kidney or urinary EGF transcript with fibrosis or kidney function decline." (PMID 30226866, 2018). "During CHC treatment, patients with SLD had distinct cytokine and growth factor kinetics, with SLD being the main source of variation in several cytokines (IL-5, IL-9, IL-10, IL-13, IL-17A, IL-22) and growth factors (EGF, VEGF and ANG), and it seems this was independent of fibrosis stage." (PMID 39200991, 2024).
liver disease (10 papers, 2013 to 2024). "The modulation of the balance between TGF-β signaling to Smad2/3 vs. pAkt (by TGF-β or EGF) has potential implications for hepatic diseases and malignancies." (PMID 38168942, 2024). "To test a broader clinical applicability of HGF/EGF mRNA-LNP to rescue liver diseases, we next evaluated the ability of HGF/EGF mRNA-LNP to accelerate liver regeneration in the well-established acetaminophen (APAP)-induced acute liver injury model." (PMID 33504774, 2021). "Epidermal growth factor (EGF) and its receptor expression are upregulated in cirrhotic liver disease." (PMID 31739536, 2019). "Our findings are consistent with prior data regarding the EGF locus and clinical outcome in liver disease." (PMID 25504078, 2014). "Together, prolonged treatment with HGF + EGF mRNA-LNP leads to sustained and robust engraftment of functional PHHs, reduces the liver disease burden, and restores overall liver function in the clinically relevant p21/NSG-PiZ model." (PMID 38866762, 2024). "Activation of the EGF receptor (EGFR)/MAPK pathway was also observed in the cPLS liver disease model in an etiology-independent manner, as shown by enhanced EGFR phosphorylation, upregulation of EGF/EGFR expression, and induction of experimentally defined EGF target gene signatures." (PMID 35801591, 2022).
necrotizing enterocolitis (10 papers, 2012 to 2024). Necrotizing enterocolitis (NEC) is a devastating disease that affects mostly the intestine of premature infants. "Systemic treatment with EGF has also shown promising results for treating neonatal necrotizing enterocolitis." (PMID 34132332, 2021). "EGF in human milk has a protective effect against neonatal intestinal diseases, such as necrotizing enterocolitis (NEC)." (PMID 28713365, 2017). "Previous studies indicated that EGF has a potential role in the prevention of necrotizing enterocolitis- (NEC-) induced TJs disruption in neonates, including humans and rats." (PMID 27524860, 2016). "While EGF is responsible for the well-being of intestine mucosa, it is considered one of the protective factors against necrotizing enterocolitis (NEC)." (PMID 38794725, 2024). "EGF plays a role in the prevention of necrotizing enterocolitis (NEC), the downregulation of proinflammatory cytokines, the upregulation of anti-inflammatory cytokines and in the maintenance of intestinal barrier function." (PMID 32599899, 2020). "In early life, milk EGF seems to be one of the crucial components involved in the prevention of necrotizing enterocolitis (NEC)." (PMID 30150532, 2018). "Epidermal growth factor (EGF) is a ligand of EGFR, and EGF supplementation has been shown to block autophagy in IEC-6 cells and in a neonatal rat model of necrotizing enterocolitis." (PMID 29403451, 2017).
pancreatic adenocarcinoma (10 papers, 2005 to 2025). "In our working model, activation of TRPM7 by various stimuli modulates intracellular Mg2+ and/or Ca2+ levels and interact with the epidermal growth factors (EGF-) induced signaling pathways, resulting in cell cycle progression, cell survival, and cell migration in pancreatic adenocarcinoma." (PMID 24278689, 2012). "We tested this hypothesis by investigating the role of EGF in mediating adhesion to and invasion through collagen I and Matrigel in the metastatic pancreatic adenocarcinoma cell line Capan-1." (PMID 15801978, 2005). "In pancreatic adenocarcinomas, Fibulin-3 binds EGFR (competitive to EGF) causing autophosphorylation of EGFR at Tyr-992 and Tyr-1068 and the subsequent phosphorylation of AKT at Thr-308 and ERK at Thr-202 and Tyr-204 and, thus, accelerates pancreatic adenocarcinoma growth." (PMID 23936443, 2013).